AXIN2 (axin 2)
Diseases named in the same sentence as AXIN2 in open-access papers (continued):
Sharing a sentence is not in itself a finding about the gene and the disease.
tumor (continued). "Furthermore, Ctnnb1 expression was increased in tumours compared to both FL and RD livers and among the components of the β-catenin destruction complex, Axin1 and the known β-catenin target Axin2 was significantly upregulated, while Apc, Gsk3a and Gsk3b were not differentially expressed." (PMID 37907668, 2023). "Hence, we speculated that under hypoxic conditions, TCF1 is upregulated in NK cells, affecting NK cell granzymes’ expression, thereby weakening NK cells’ killing effect on tumor cells through regulating AXIN2." (PMID 38035113, 2023). "However, it should be noted that AXIN2 was previously identified as a potent tumor promoter instead of a suppressor, as it was found to exert global control over gene expression networks which were critical for tumor-invasive and metastatic behavior." (PMID 35237578, 2022). "RNF43 and AXIN2 are negative regulators of the Wnt-ligand dependent type of CRC and their downregulation in MSI samples might suggest an association of Wnt ligand dependent pathogenesis in a subset of tumours." (PMID 34824625, 2021). "Of note, 4βHWE treatment suppressed the expression of the c-Myc, Axin2, cyclin D1, and survivin Wnt target genes in the tumor tissues, as well as the induction of Ser33/Ser37/Thr41 phosphorylation of β-catenin, indicating that 4βHWE inhibits Wnt signaling in vivo to attenuate tumor proliferation." (PMID 30909473, 2019). "However these data do not support a major role of Wnt signaling or of Axin2 in carcinoma associated fibroblasts and tumor growth." (PMID 27555909, 2016). "A likely explanation for this difference in findings may be the differences in the biological models used, as the previous publication which reported increased AXIN2 expression following ROR2 silencing used in vivo mouse models incorporating the tumour microenvironment." (PMID 27440078, 2016). "Therefore, we examined protein expression of active β-catenin and Axin2 in tumor tissues." (PMID 25980501, 2015). "Interestingly, on average, the AXIN2 CGI was significantly less methylated in tumours compared with the matched apparently normal mucosa, and in only one tumour, it was more methylated than in matched apparently normal mucosa from the same person (6.8 vs 3.5%)." (PMID 18542073, 2008). "Next, to demonstrate the selective differentiation-inducing effect of VPA in tumor cells, we evaluated the expression of the CSC markers Sox9, Axin2, Cd44, and Ascl2 in organoids isolated from healthy mouse intestines." (PMID 40750758, 2025). "Borealin overexpression enhances tumor growth and metastasis by downregulating the RNF43 and AXIN2 expression levels and activating β-catenin, thereby decreasing the survival rate of patients with hepatocarcinoma." (PMID 41487817, 2025). "To investigate TIC-derived GAS6 suppression of tumor immunity via AXL/MERTK on Reg-TAMs, we used Krt19-DreER Axin2-creER R26-Ai66 mice for AKT/YAP/SB hydrodynamic injection and sorted Reg-TAMs and epithelial cell adhesion molecule+/Tom+ (EpCAM+Tom+) TICs." (PMID 39774471, 2025). "The embryonal HBTOs were enriched with WNT target genes and EMT markers, including AXIN2, LEF1, DKK1, NOTUM, NKD1 and VIM, in line with the embryonal tumor signature." (PMID 39567475, 2024). "There were almost no FGF19-expressing cells that did not also express either AXIN2 or SOX4, suggesting that FGF19 expression is a unique feature of a subset of AXIN2+, SOX4+ tumor cells." (PMID 39567523, 2024). "We further examined the anti‐tumor effect of DU101 and DU102 in our previously used liver CSC transgenic mouse model, Axin2‐CreER driven MYC‐ON liver tumor mouse model." (PMID 39225354, 2024).
tumor (continued). "Although we did not detect LINC00313 over-expression in CCA tissues, the expression levels of ACTL6A, TCF7, WNT5A, AXIN2 and SULF2 were all increased in CCA human tumours (Fig. EV5B)." (PMID 38332153, 2024). "In addition, compared to the control group tumor cells, melittin treatment resulted in a reduction in β-catenin protein levels and an increase in Axin2 protein levels, reminding us that melittin may regulate the EMT process through the β-catenin signaling pathway." (PMID 39519238, 2024). "On the other hand, CTNNB1 knockdown inhibits the Wnt/β-catenin signaling pathway and downregulates the expression of downstream genes, including axin 2, lymphoid enhancer-binding factor 1 (LEF1), and cyclin D1, thereby inhibiting tumor proliferation." (PMID 37033970, 2023). "Tumor cells from patient #4001 were characterized by overexpression of AFP, GPC3, DUSP9, DLK1, GLUL, and AXIN2, a marker of Wnt/β-catenin pathway activation." (PMID 37932266, 2023). "Second, the overexpression of FRA1 downregulated the expression of the following genes involved in transformation and tumor promotion: WNT9A, AXIN2, and MYB." (PMID 37830558, 2023). "The expression of classical CTNNB1‐dependent transcriptional Wnt targets such as AXIN2 and NKD1 was elevated in a large fraction of tumor samples compared with normal tissue." (PMID 35904277, 2022). "Western blot analysis revealed decreased Axin2 and Snail expression both in the pLKO-Tet-shAxin2 vector-transfected IHOK line and tumor nodules from groups treated with doxycycline compared with that in controls." (PMID 35875099, 2022). "Among these genes, PLK1, CDC25C, ESCO2, AXIN2, TREX2, ALKBH2, and MC1R were upregulated in tumor tissues, whereas IGF1 and ESR1 presented downregulation." (PMID 35484177, 2022). "Validating these findings, we found expression of canonical WNT target genes AXIN2, LGR5, TCF7 and ASCL2 were elevated in tumours expressing high levels of RAC1B." (PMID 33879799, 2021). "Considering that E-cadherin/α-catenin tumor suppressors strongly induce YAP phosphorylation as an upstream regulator of the Hippo, these results indicate that Axin2 specifically inhibits the Hippo pathway in CRC." (PMID 34298652, 2021). "Immunostaining for β-CATENIN and in situ hybridization for AXIN2 in PDX4 showed that after ICG-001 treatment, tumor tissues displayed a reduced expression of these markers, in contrast to vehicle-treated controls." (PMID 32066735, 2020). "Intestinal tumor suppressor CDX2 activated AXIN2 promoter activities via intestinal cell-specific enhancer elements to inhibit WNT signaling pathways and prevent tumor invasion and migration." (PMID 33401247, 2020). "The exception to this rule is a strengthened correlation between AXIN2 and TCF7 expression in tumor tissue." (PMID 32403323, 2020). "Target genes AXIN2, DKK2 and FGF9, well known for their potential to promote tumor formation and progression in vitro as well as in vivo in CRC, were significantly downregulated in response to SARB46,47." (PMID 31097715, 2019). "Three genes, AXIN2, DKK3, and SFRP1, which are known as tumor suppressors in a broad range of human malignancies including NSCLC, are targeted by miR-582-3p and suppress their protein levels." (PMID 30621620, 2019). "In silico analysis showed that variations in AXIN2 found in CRC patients, were more frequently in earlier stages of tumor and patients who carry variations in the AXIN2 gene have a worse prognosis (p < 0.05)." (PMID 31632692, 2019). "Supporting the notion that these modules represent specific signatures, genes known to be expressed in tumour epithelium, such as WNT targets (e.g. AXIN2, NOTUM), FGF3 and BMP4 were contained in the brown module [Suppl." (PMID 29541918, 2018). "Western blotting revealed that the expression of β‐catenin, TCF1, cyclin D1, AXIN2 and MMP7 was remarkably reduced in shTRIM32‐inoculated tumour tissues." (PMID 30079558, 2018).
tumor (continued). "Celecoxib treatment also decreased the expression levels of Wnt pathway components and target genes, such as β-catenin, p-GSK-3β, MMP-2, Survivin, AXIN2, CYCLIN-D1 and C-MYC, and the CSC marker SOX-2 in the xenograft tumor tissues." (PMID 29383157, 2017). "Comparing papCP and adaCP tumor samples, the latter showed significant up-regulation of direct targets of the Wnt/β-catenin signaling pathway (LEF1 and AXIN2) as well as important components of the hedgehog signaling pathway (GLI2, PTCH1 and SHH)." (PMID 26927026, 2016). "AXIN2, DKK3 and SFRP1 have been identified as negative regulators of Wnt signalling and suggested to be tumour suppressors in a broad range of human malignancies including NSCLC14." (PMID 26468775, 2015). "Overall, our results demonstrate that miR-582-3p activates Wnt signalling by targeting AXIN2, DKK3 and SFRP1; enhances stem cell-like traits; and leads to tumour recurrence and poor prognosis in NSCLC patients." (PMID 26468775, 2015). "In vivo, on established tumor xenografts in athymic nude mice, 9 days of β-catenin silencing resulted in a significant reduction of CTNNB1 and AXIN2 expression." (PMID 23409032, 2013). "YW210.09 antibody also inhibits endogenous Wnt1 signaling in cultured tumor cells grown from MMTV-Wnt1 tumors, as observed by reduced expression of Wnt target genes Axin2 and Mmp7 to a similar extent as Fzd8CRD-Fc protein treatment." (PMID 20856934, 2010). "RNA sequencing demarcated tumor models from normal liver cells by displaying high levels of the HB markers GPC3, AFP and IGF2, the proliferation marker Ki67, and the Wnt signaling target AXIN2." (PMID 39529166, 2024). "Treatment with Plenish oil-rich diet had no significant influence on the expression of Jun, Pcna, Ki67, Myc, Vegf, Axin2, and β-catenin, supporting that Plenish oil-rich diet did not significantly affect the on expression of tumor markers in colon tissues." (PMID 35804751, 2022). "(A) Relative expression of Axin2 transcripts in tumor-propagating cells (TPCs) and non-TPC following EHMT2 inhibition (EHMT2i) vs vehicle control (control) (n=4 mean± SEM; two-tailed paired t-test, *p<0.05)." (PMID 35983994, 2022). "Axin2, as a component of the β-catenin degradation complex under the absence of Wnt signals, was initially identified as a tumor suppressor gene." (PMID 36324094, 2022). "Material from the regrown tumor was collected to establish an isogenic model of carboplatin-resistant TNBC (C4O) and gene expression analysis revealed changes in Wnt signaling target AXIN2 and pluripotency and stem markers NANOG, OCT4, SOX2, and LGR5." (PMID 34367990, 2021). "ZHFX3, BIRC6, Axin2, CPEB3 and TPR can regulate the proliferation and apoptosis of tumor cells." (PMID 35087829, 2021). "In the PDTX model, administration of SR3029 obviously delayed tumor growth, concomitant with an increased protein level of AES and a decreased expression of Wnt target genes (Axin2, Fibronectin and LEF1), stemness marker genes (CD44 and LGR5) and Notch target genes (HES1 and HES2)." (PMID 33754069, 2021). "Epigenetic suppression of appropriate Wnt negative feedback loops is selectively advantageous in LD tumours and differential AXIN2 expression in LD/LI lesions can be exploited as a molecular biomarker." (PMID 31563876, 2020).
tumor (continued). "Our meta-analysis reveals that AXIN2 is consistently expressed at a higher level in tumor relative to normal tissue, and so is LGR5, indicating as expected increased Wnt/β-catenin signaling activity and increased stem cell identity of tumor tissue." (PMID 32403323, 2020). "Next, we scored AXIN2 IHC staining on available sections (n=53) using two complementary approaches: automated scoring using the HALO digital pathology platform and manual scoring by expert histopathologist in a random subset of tumours (n=27)." (PMID 31563876, 2020). "However, the four tumours with known LD status (RSPO-fusion n=3, RSPO-high n=1) had comparably low manually scored AXIN2 protein expression." (PMID 31563876, 2020). "The tumor suppressor function of AXIN1 and AXIN2 proteins in the Wnt signaling pathway has long been hypothesized, based largely on their roles in the β-catenin destruction complex." (PMID 31143301, 2019). "Our findings of high expression of Cyclin D1 and significantly higher expression of AXIN2, LEF1 and ZNRF3 mRNA in tumours harbouring the ∆(2 + 3) deletion at a similar level to those with hot spot mutations suggest the activating nature of these deleterious mutations in ACCs." (PMID 29872083, 2018). "Moreover, both AXIN2 and MUTYH are expressed in N14-77 samples at a level resembling other canine intestinal normal and tumor samples." (PMID 30018743, 2018). "We did also not observe a major difference in tumor weight (Axin2+/lacZ: 166/86-215; Axin2+/+: 283/125–382 median/interquartile range in mg) between mice lacking one or none allele of Axin2." (PMID 27555909, 2016). "We did also not observe an obvious influence of Axin2 function on the tumor weight when comparing tumors grown in Axin2+/lacZ to tumors grown in AxinlacZ/lacZ." (PMID 27555909, 2016). "Although Axin2 is known as a canonical Wnt suppressor, an increasing number of studies have shown that it promotes oncogenic activity rather than functioning as a tumour suppressor 45,46." (PMID 25787115, 2015). "Furthermore, we found that the repression efficacy of silencing miR-1207 on tumor sphere formation was dramatically abolished by downregulation of SFRP1, AXIN2 and ICAT." (PMID 26337084, 2015). "Selected CRC target genes involved in apoptosis (BAX), tumor growth (TGFβRII), WNT pathway (AXIN2, TCF4, WISP3), DNA repair (ATM, ATR, BLM, BRCA1, BRCA2, DNAPKcs, MBD4, MRE11, MSH3, MSH6, RAD50, XRCC2) and PI3-kinase signaling (PTEN) were analyzed for mutations in MSI-positive HGG samples." (PMID 21637783, 2011). "However, TBX3 expression only partially overlapped with that of other Wnt target genes such as AXIN2 and LGR5, suggesting varying levels of Wnt activation across tumor types, and mechanisms of uncoupled regulation between TBX3 and other targets depending on the context." (PMID 40343989, 2025). "AXIN2, a negative inhibitor of the Wnt signalling pathway, regulates the phosphorylation and degradation of β‐catenin, thus promoting the overexpression of target genes, affecting cell proliferation and differentiation, and promoting the occurrence of tumours." (PMID 37488774, 2023). "Axin2 does not act as a tumor suppressor, but acts as an effective promoter of cancer behavior by up-regulating the activity of the transcriptional suppressor Snail1, inducing the functional epithelial-mesenchymal transition (EMT) program and driving metastatic activity." (PMID 35836256, 2022). "AXIN2 and RNF43 are negative regulators of WNT signaling that are transcriptionally activated by nuclear β-catenin, consistent with the notion that epigenetic silencing of negative regulators plays a critical role in tumor formation in ligand-dependent, APCmut– CRCs." (PMID 34873211, 2021).
tumor (continued). "In consistence with our previous findings, the results showed that ATP6AP2 expression is higher in tumor tissues than that in normal tissues, moreover, level of ATP6AP2 transcripts in COAD is positively correlated with those of LRP6, CTNNB1, MYC, CCND1 and AXIN2." (PMID 32143717, 2020). "The direct comparison between the AXIN2- and all TCF7L1 gene expression-correlated transcriptomes confirms the higher correlation of TCF7L1 expression with cell adhesion-associated transcripts, not just in normal tissue, but also in tumor tissue." (PMID 32403323, 2020). "Similarly, tumor mRNA levels of β‐catenin target genes Axin2 and Plau were not different between the control and aspirin groups." (PMID 31994315, 2020). "Thus, we presumed that the mechanism of AXIN2 regulating T cells CD8 and T cells CD4 memory resting might have an influence on tumor progression and metastasis." (PMID 31681739, 2019). "Additionally, in-depth molecular-level investigations have demonstrated that CDX2 can reduce the expression of downstream target genes, including axis inhibition protein 2 (AXIN2) and lung lineage transcription factor Nkx2-1, which subsequently inhibit tumour invasion and metastasis." (PMID 29179508, 2017). "However, ablation of Axin2 had no influence on the observed β-galactosidase positive cell clusters or on tumor weight." (PMID 27555909, 2016). "Additionally, in tumor tissues collected from A549 xenograft model, ART and its derivatives effectively reduced Wnt5-a/b, LRP6, and Dvl2 but significantly increased both NKD2 and Axin2 (p < 0.001)." (PMID 27119499, 2016). "Positive correlations linking TCF7 with LEF1 and with LGR5 in normal tissue are reduced in tumor tissue, and the negative correlation between AXIN2 and TCF7L1 in normal tissue is also reduced in tumor tissue." (PMID 32403323, 2020). "Upon treatment of these tumours with anti-RSPO3 antibody using patient-derived xenograft models, expression of LGR5 and ASCL2 were highly downregulated, whereas MYC, AXIN2 and CCND1 (cyclin D1) did not rank among the top 100 downregulated genes." (PMID 30792270, 2019). "AXIN2+DKK1 methylation significantly predicted recurrence independent of age, sex, tumor size, localization, differentiation, CIMP, BRAF and KRAS mutations." (PMID 28368388, 2017). "However, in line with the lack of tumor formation in the brains of GL mice, we did not observe a significant increase in the abundance of selected Wnt and Shh targets (APC, GLI2, AXIN2, MYCN, MYC)." (PMID 34801069, 2021). "Although we observed high concentrations of drug levels in tumor 1 hour after AZ1366 administration and robust Axin2 stabilization at 8 hours, we were not able to demonstrate any decrease in active β-catenin or c-Myc, a WNT dependent gene, at all time points examined." (PMID 27070088, 2016). "Interestingly, HCC lesions but not the background liver expanded as tumour organoids in vitro by forming compact structures composed of tumoural cells that filled in the lumen of the organoid and expressed high levels of WNT target genes (Axin2 and Sp5)." (PMID 35039505, 2022).